GOT1 (glutamic-oxaloacetic transaminase 1)
Diseases named in the same sentence as GOT1 in open-access papers (continued):
Sharing a sentence is not in itself a finding about the gene and the disease.
cancer (continued). "However, the GOT1-null or down-regulated cancer cells were highly sensitive to nutrient depletion or glucose deprivation." (PMID 29751795, 2018). "Interestingly, in contrast to PDAC cells, where aspartate was converted to OAA by GOT1, cancer cells with defects in the electron transport chain reversibly used GOT1 to provide aspartate from OAA to maintain cell growth." (PMID 29751795, 2018). "Increased expression of GOT1 was also observed in cancer cells exposed to large EVs as little as 2 h following exposure, suggesting that the protein might be transferred to recipient cells specifically via large EVs." (PMID 25857301, 2015). "Targeting GOT1 or disruption of this pathway has been reported to cause a decrease in the NAD+/NADH ratio, increase in the NADP+/NADPH ratio and reduced ATP production, collectively contributing to suppression of cancer cell proliferation and enhancement of sensitivity to anti-tumor therapies." (PMID 41299514, 2025). "Therefore, GOT1 has become a key consideration when interrogating cancer metabolism." (PMID 39777342, 2024). "Furthermore, GOT1-metabolic pathways have also been shown to play a role in other cancers, indicating that GOT1 inhibitors may have utility beyond PDA." (PMID 31908776, 2020). "Therefore, the blood dihydroorotate/orotate may be a potential biomarker for cancer diagnosis, and the involved metabolic enzymes, such as CAD and GOT1, could be potential targets for cancer treatments." (PMID 30643150, 2019). "GOT1 might be a useful candidate target for treatment of cancers with high GOT1 expression." (PMID 29751795, 2018). "Therefore, studies of GOT1 may give new insights in cancer cell metabolism, and may also provide novel targets for cancer treatment." (PMID 29751795, 2018). "However, we also found GOT1 significantly decreased in other types of cancers." (PMID 29751795, 2018). "Our findings suggest that perturbations in the levels of GOT1/GOT2 within specific tissues reflect pathophysiological changes beyond tissue damage and have implications for cancer metabolism, immune infiltration, prognosis, and treatment personalization." (PMID 42245720, 2026). "Inhibiting glutamic-oxaloacetic transaminase 1 (GOT1) is a strategy to target glutamine metabolism and impair cancer cell functions." (PMID 41527462, 2026). "In terms of mechanism, GOT1 can upregulate the expression of the C–C motif chemokine receptor-2 (CCR2), thereby activating the Nrf2/HO-1 axis to resist ferroptosis in cancer cells." (PMID 38166927, 2024). "GOT1/GOT2, GPT1/GPT2, and PSAT are important enzymes in glutamine metabolism and amino acid biosynthesis, and have crucial functions in various types of cancers." (PMID 36959802, 2023). "Compared with normal tissues, the expression of FRGs with higher amplification frequency increased significantly in cancer tissues (e.g., SQLE, NFS1, and ACACA), and vice versa (e.g., GOT1, HMGCR, and FTH1)." (PMID 35444656, 2022). "Cancer cells import it via a cell-specific SLC1A3, an aspartate/glutamate transporter, or synthesize it from cytosolic oxaloacetate via GOT1 (glutamate-oxaloacetate transaminase 1)." (PMID 34829708, 2021). "We report that inhibition of GOT1 suppresses the growth of numerous PDA cell lines, primary cancer models, and xenograft tumors, while rendering some PDA cells susceptible to ferroptosis." (PMID 34381026, 2021). "Glutamate oxaloacetate transaminase 1 (GOT1) mainly regulates cellular glutaminolysis, which converts glutamate (Glu) into a-ketoglutaric acid (a-KG) and is crucial for sustaining cancer progression." (PMID 33276753, 2020). "We have identified a panel of six proteins viz., GOT1, HNRNPA2B1, MAPK1, PAK2, UBE2N, and YWHAB, which contribute to cancer development, and the transition of PCa from androgen dependent to independent stages." (PMID 32322560, 2020).
cancer (continued). "Enzymes utilized for glutamine metabolism in PDA, GLS1, GOT1/2, and malic enzyme 1 (ME1) (see pathway), in addition to NQO1, were significantly upregulated in PDA compared to 17 other cancers when assessed using the Oncomine webtool." (PMID 26462257, 2015). "Collectively, these studies indicate that in the absence of GOT1, cells possess both endogenous and exogenous compensatory mechanisms that allow cancer cells to survive." (PMID 39777342, 2024). "Moreover, several inhibitors of GOT1 and GPT2, likely Hydralazine hydrochloride, Aspulvinone O, Oxamate and Aminooxyacetate, were reported to reduce growth in different cancer lines." (PMID 37445598, 2023). "Glutamic-oxaloacetic transaminase 1 (GOT1) plays a vital role in the production of non-essential amino acids in glutamine metabolism, which is necessary for cell proliferation of various cancers." (PMID 33832516, 2021). "YAP is also an activator of the glutamate-related aminotransferases glutamic-oxaloacetic transaminase 1 (GOT1) and phosphoserine aminotransferase 1 (PSAT1), which mediate the conversion of glutamate to α-ketoglutaric acid (α-KG), thereby stimulating cancer cell growth." (PMID 34765600, 2021). "However, knockdown of CAD or GOT1 strongly, while DHODH knockdown marginally, sensitized cancer cells to hypoxia." (PMID 30643150, 2019). "Interestingly, we find that CSA is differentially metabolized in cancer cells and mouse embryonic fibroblasts, which correlates with differential expression of CSAD and GOT1." (PMID 31107239, 2019). "Moreover, we show that GOT1 plays an important role in protecting CRC cells against OXPHOS inhibition, proposing GOT1 targeting as a potential strategy to improve the therapeutic efficacy of OXPHOS inhibitors in cancer treatment." (PMID 39809754, 2025). "Supplementation with the metabolites aspartate and α-ketoglutarate (α-KG) has been shown to rescue cancer cell proliferation by GOT2 inhibition, and another study reported that supplementation with the GOT1 downstream metabolite oxaloacetate could partially rescue viability of GOT1-knockout cells." (PMID 41299514, 2025). "Moreover, none of these GOT1 inhibitors have progressed to clinical trials yet, necessitating further research to develop effective GOT1 inhibitors for cancer treatment." (PMID 39777342, 2024). "Therefore, the inhibition of glutamine uptake by the glutamine transporter (ASCT2), as well as the inhibition of glutaminase, GDH, GOT1 and GPT2, seem to all be good strategies to decrease the replenishment of intermediates in the TCA cycle and, consequently, cancer cell proliferation." (PMID 37445598, 2023). "Interestingly, studies have shown that the electron transport chain inhibition in cells lacking GOT1 reduces cell growth, thus providing evidence for the reliance of these cancers on OXPHOS metabolism." (PMID 33946867, 2021). "However, a rigorous comparison of GOT1 sensitivity in different cancer types has not been performed." (PMID 31908776, 2020). "Although cancer cells with defects in electron transport chain were able to produce aspartate from OAA to support proliferation, addition of aspartate could not rescue either the GOT1-null or GOT1 siRNA knockdown A549 cancer cells." (PMID 29751795, 2018). "Because GOT1 catalyzes the reversible conversion from aspartate and α-ketoglutarate to glutamate, we used a functional assay that measures the production of glutamate per unit time as an indication of GOT activity in cancer cells exposed to large and nano-sized EVs." (PMID 25857301, 2015). "Genes involved in the glutamine-dependent transamination pathway (GLS1, GOT1/2, ME1) and NQO1, but not GLUD1, are highly expressed in PDA relative to other cancers." (PMID 26462257, 2015).
infection (15 papers, 2011 to 2025). The state of being infected such as from the introduction of a foreign agent such as serum, vaccine, antigenic substance or organism. "GOT1 exhibited a biphasic expression pattern: levels gradually increased during early-to-mid infection (3–12 hpi), peaked at 12 hpi, and declined to basal levels during late infection (18–24 hpi)." (PMID 41171159, 2025). "Next, we performed pathogens infection in vivo to test the role of Got1-mediated ROS production in Got1f/f and Got1ΔLysM mice." (PMID 38965342, 2024). "Above results indicated that SCRV infection mainly promoted the expression of GOT1 in the early stage, and promoted the expression of MDH2, GOT2, and ASNS in CPB cells in the late stage." (PMID 37065159, 2023). "Because the expression levels of GOT1 transiently increased on day 8 after LCMV Armstrong infection, we investigated the potential role of GOT1 in regulating the formation of effector CD8+ T cells during LCMV Armstrong acute infections." (PMID 37813964, 2023). "The transcription initiation site (TIS) of Got1 was constantly accessible before and after infections, thereby suggesting that LCMV infection induced the expression of Got1 at the transcriptional level but not the epigenetic level." (PMID 37813964, 2023). "Viral titers were comparable between the ‘Got1 WT’ group and the ‘Got1 KO’ group on day 8 after LCMV clone 13 infections." (PMID 37813964, 2023). "To elucidate ASFV’s regulatory strategy over GOT1 and GOT2, we mapped the kinetics of their protein expression at various time points post-infection." (PMID 41171159, 2025). "ISKNV mainly promoted the expression of MDH1, GOT1, MDH2 and GOT2 in the early stage of infection and further facilitated energy supply, ultimately promoting the proliferation of ISKNV." (PMID 39459874, 2024). "Our results confirmed that SCRV infection upregulated the expression of malate-aspartic acid shuttle MDH1/2 and GOT1/2." (PMID 37065159, 2023). "Ki-67 protein levels were lower in Got1 KO than WT CD8+ T cells, thus suggesting that virus-specific CD8+ T cells required GOT1 to proliferate during LCMV clone 13 infection." (PMID 37813964, 2023). "To examine the potential role of GOT1 in antiviral CD8+ T cell responses, we adoptively transferred Got1 KO or WT P14 CD8+ T cells into C57BL/6 host mice before LCMV clone 13 infection." (PMID 37813964, 2023). "The DEGs involved in amino acid biosynthesis and energy metabolic processes were GOT1, CBSL, SOCS1, LPL and STC2, and their expressions were largely down‐regulated in response to H37Rv infection." (PMID 34632719, 2021). "Among these genes, glutaminase 1 (GLS1) and glutamate dehydrogenase 1 (GLUD1) enzyme activity and protein expression were elevated, while glutamic oxaloacetic transaminase (GOT1 and GOT2), glutamate pyruvate transaminase 2 (GPT2), and glutamine synthase (GS) were unchanged during PoRVA infection." (PMID 38905309, 2024). "The percentages of Got1 KO donor T cells among the total CD8+ T cells in the C57BL/6 host mice, as well as the absolute numbers of Got1 KO donor T cells, were lower than those of Got1 WT donor T cells at day 8 and day 30 after infection." (PMID 37813964, 2023). "However, using receiver operating characteristic curves, we identified four to 48 candidate biomarkers of infection depending on the pathogen, including seven overlapping biomarkers (DSG2, PCBP1, MGAM, APOA4, DPEP1, GOT1, and IGFALS)." (PMID 38193073, 2023). "infections; APOA4, DPEP1, and GOT1 were negative predictors while IGFALS was a positive predictor." (PMID 38193073, 2023).
cardiovascular disease (6 papers, 2016 to 2024). "Of particular interest was the observation that only a few of the most significantly up/downregulated proteins such as the superoxide dismutase (SOD2), HSP90AA1 or GOT1, could be allotted a cardiac-related function, or may have been implicated in cardiovascular disease thus far." (PMID 27711126, 2016).
infectious disease (1 paper, 2023). A disorder directly resulting from the presence and activity of a microbial, viral, or parasitic agent in humans. "Got-1, Got-2, and Hpd genes are involved in metabolic changes associated with inflammatory processes and infectious diseases when it is needed to modify protein and amino acid requirements." (PMID 36835523, 2023).
nervous system disease (1 paper, 2020). "For instance, in OPC protein–protein interaction (PPI) network, proteins involved in Golgi vesicle transport (such as Vamp3, Golga7, Vti1b and Snx1), Cell redox homeostasis (such as Tnx2 and Gsr), nervous system disease (such as Got1, Gm2a, Apoe and Cst3) and other functions were identified." (PMID 32974003, 2020).
GOT1 also shares sentences with these, for which no sentence is quoted: dengue (13 papers); Thrombocytopenia (10); COVID-19 (6); liver dysfunction (6); chronic kidney disease (5); chronic obstructive pulmonary disease (5); Hypertension (5); liver disease (5); acute kidney injury (4); leukopenia (4); Arthritis (3); atherosclerosis (3); Cirrhosis (3); Encephalopathy (3); heart disease (3); Hyperbilirubinemia (3); hyperlipidemia (3); Hypoglycemia (3); Insulin resistance (3); liver failure (3); neuroendocrine tumors (3); neutropenia (3); Obesity (3); renal failure (3); type 2 diabetes (3); acute viral hepatitis (2); anemia (2); Anxiety (2); bacterial infection (2); bleeding disorder (2).
A further 111 diseases each share a sentence with GOT1 in 2 papers or fewer.